HMGA1 (high mobility group AT-hook 1)
Diseases named in the same sentence as HMGA1 in open-access papers (continued):
Sharing a sentence is not in itself a finding about the gene and the disease.
mesenchymal tumours (5 papers, 2008 to 2023). "The description of miRNA-mediated HMGA protein regulation begins with the finding that chromosomal abnormalities in the regions 12q15 and 6p21.3 were associated with the aberrant expression of either HMGA2 or HMGA1 in several benign mesenchymal tumours." (PMID 31979076, 2020). "In humans chromosomal aberrations affecting the HMGA1 gene locus on HSA 6p21 were described to be the cause for various benign mesenchymal tumours while high titres of HMGA1 proteins were shown to be associated with the neoplastic potential of various types of cancer." (PMID 18651940, 2008). "HMGA2 rearrangements are well known in several mesenchymal tumors, conversely little is known about the expression and function of HMGA1 in these tumors." (PMID 29980789, 2018). "The HMGA2 gene immediately appeared to be more complex than the HMGA1 gene, essentially due to its length and the presence of a very large intron involved in rearrangements, leading to truncated or chimeric HMGA2 transcripts especially in benign mesenchymal tumours." (PMID 31979076, 2020).
metabolic syndrome (5 papers, 2013 to 2022). A cluster of metabolic risk factors for CARDIOVASCULAR DISEASES and TYPE 2 DIABETES MELLITUS. "In humans, the HMGA1 IVS5-13insC variant (rs146052672), which resulted in a decrease in mRNA and protein levels of HMGA1, was significantly associated with metabolic syndrome and negatively correlated with serum HDL-cholesterol." (PMID 35805937, 2022). "Besides its effects on glucose homeostasis, HMGA1 plays a role in adipogenesis and lipid metabolism, while the HMGA1 rs139876191 variant correlates with body mass index, and reduced HDL levels in patients with metabolic syndrome and type 2 DM." (PMID 29387042, 2018). "Defects in HMGA1 protein, or the association with functional HMGA1 variants, among which the most common rs139876191 variant (previously named rs146052672), cause a decrease in INSR expression and a trans-ethnic increased susceptibility to either type 2 DM or metabolic syndrome." (PMID 29387042, 2018).
pulmonary arterial hypertension (5 papers, 2020 to 2024). Pulmonary arterial hypertension (PAH) is a group of diseases characterized by mean pulmonary artery pressure >20 mmHg and elevated pulmonary arterial resistance leading to right heart failure. "It is reported that the levels of the chromatin-associated transcriptional regulator, HMGA1, increase in IPAH ECs, which induces EndMT in pulmonary hypertension; knockdown of HMGA1 inhibits EndMT gene expression induced by loss of BMPR222." (PMID 32371931, 2020). "Decreased or dysfunctional BMPR2 expression increased high mobility group AT-hook 1 (HMGA1) expression, leading to EndMT in PAEC and promoting occlusive remodeling of idiopathic pulmonary hypertension." (PMID 36419957, 2022). "In contrast to non-tumor conditions, higher HMGA1 expression has been correlated with lower expression of CD31 in a mouse model of pulmonary hypertension." (PMID 35629376, 2022).
seminoma (5 papers, 2020 to 2022). A radiosensitive malignant germ cell tumor found in the testis (especially undescended), and extragonadal sites (anterior mediastinum and pineal gland). "In fact, it has been shown that PATZ1 interacts with ERβ in normal germ cells, while the downregulation of ERβ associates with PATZ1 and HMGA1 cytoplasmic delocalization in seminomas." (PMID 33573132, 2021). "They referred to the Cancer Genome Atlas database, showing low expression of Let-7a and miR-26a in human seminoma, and an inverse corelation with HMGA1 expression." (PMID 35267498, 2022). "By using the Cancer Genome Atlas database, Let-7a and miR-26a have been found to be downregulated and negatively correlated with HMGA1 expression levels in human seminoma." (PMID 34440480, 2021). "Starting from a set of already validated HMGA1-targeting miRNAs, we focused on the role of miR-26a and Let-7a in human seminomas." (PMID 32344629, 2020). "Results: an inverse correlation was found between the expression of miR-26a and Let-7a and HMGA1 expression levels in seminomas samples, suggesting a critical role of these microRNAs in HMGA1 levels regulation." (PMID 32344629, 2020). "Conclusions: these data strongly support that the upregulation of HMGA1 levels occurring in seminoma is—at least in part—due to the downregulation of HMGA1-targeting microRNAs." (PMID 32344629, 2020). "Moreover, they demonstrated that Let-7a and miR-26a were able to inhibit seminoma cell growth and mobility by inhibiting HMGA1 levels." (PMID 33573132, 2021). "In functional studies using human seminoma cell line TCam-2, the authors also reported that Let-7a and miR-26a play a critical role in inhibiting seminoma cell growth and motility by directly regulating HMGA1 expression." (PMID 34440480, 2021). "Finally, functional assays confirmed that miR-26a and Let-7a inhibit the proliferation and motility of a seminoma cell line by targeting HMGA1, therefore suggesting a critical role of their downregulation in testicular tumorigenesis." (PMID 32344629, 2020). "In the present work, we evaluated the correlation between HMGA1 mRNA, Let-7a and miR-26a expression levels in a seminoma dataset available in the Cancer Genome Atlas (TCGA) database (n = 65), since several studies reported that HMGA1 mRNA levels are negatively regulated by both Let-7a and miR-26a." (PMID 32344629, 2020). "To test whether these miRNAs are able to target HMGA1 also in seminoma, we transfected miR-26a and Let-7a into the seminoma cell line TCam-2 and we searched for fluctuations in HMGA1 amounts by western blot analysis." (PMID 32344629, 2020). "Thus, the aim of this study is to test whether HMGA1 overexpression in human seminomas may be induced by the deregulation of miR-26a and Let-7a—two HMGA1-targeting microRNAs." (PMID 32344629, 2020). "Therefore, the aim of our research work was to investigate whether HMGA1 overexpression, occurring in human seminomas, may be dependent on the deregulation of HMGA1-targeting miRNAs." (PMID 32344629, 2020). "Interestingly, both Let-7a and miR-26a levels were found negatively correlated with HMGA1 expression levels, which our previous studies demonstrated to be upregulated in human seminoma, thus suggesting a negative control exerted by these miRNAs on HMGA1 transcript in human seminoma." (PMID 32344629, 2020).
virus infection (5 papers, 2017 to 2025). "We have previously reported that HMGA1 plays a significant role in BoHV-1 productive infection in cell cultures, although the mechanisms underlying this role in viral infection remain not fully understood." (PMID 39769030, 2024). "This is the first report suggesting that HMGA1 may be implicated in virus infection-induced DNA damage, although the precise mechanism remains to be elucidated." (PMID 39769030, 2024). "HMGA1 does indeed modulate the nuclear accumulation of 53BP1 protein, but this effect is counteracted by virus infection." (PMID 39769030, 2024). "The expressions of virion-associated proteins, labeled as 1, 2, 3, 4, and 5 respectively, were clearly detected at 16 and 24 h post infection (hpi), confirming that virus infection accounts for the alteration of HMGA1 protein expression." (PMID 39769030, 2024). "Collectively, these results indicate that HMGA1 is involved in countering DNA damage induced by virus infection." (PMID 39769030, 2024). "This increase in nuclear HMGA1 accumulation was consistent with the elevated expression in the whole cell extracts observed following virus infection." (PMID 39769030, 2024). "In summary, for the first time we reported that HMGA1 is potentially involved in countering DNA damage induced by virus infection." (PMID 39769030, 2024). "Inflammatory mediators also induce HMGA1 expression, such as viral infection, or lipopolysaccharide (LPS), which also activate other inflammatory cytokines." (PMID 34572547, 2021). "Following viral infection or LPS, for example, HMGA1 orchestrates the assembly of NF-κB subunits, p50 and p65, to the IFNβ promoter, inducing IFNβ expression and secretion." (PMID 34572547, 2021). "Following shRNA virus infection with the shC1-2 clone, the expression level of HMGA1 mRNA was significantly knocked down by nearly 70% in both PC9 and PC9/gef cells." (PMID 28290473, 2017). "Furthermore, we report for the first time an interaction between HMGA1 and 53BP1, which is disrupted following virus infection." (PMID 39769030, 2024). "Consequently, a 24 h virus infection period was chosen to analyze the subcellular localization of HMGA1 protein in response to BoHV-1 infection." (PMID 39769030, 2024). "Therefore, any reduced expression due to shRNA or AAT virus infection would not block that action of the already expressed HMGA1, which would, however, be impacted by the sequestration strategy." (PMID 41183073, 2025). "However, the biological function of HMGA1 in countering virus infection-induced DNA damage appears to be independent of its regulation of the 53BP1-dependent DNA damage repair." (PMID 39769030, 2024). "Therefore, the biological function of HMGA1 in countering virus infection-induced DNA damage may be independent of its regulation of 53BP1 signaling." (PMID 39769030, 2024).
acute myocardial infarction (4 papers, 2018 to 2025). Necrosis of the myocardium, as a result of interruption of the blood supply to the area. "The HMGA1 rs146052672 variant was shown to be associated with myocardial infarction susceptibility." (PMID 34659644, 2021).
clear cell renal cell carcinoma (4 papers, 2022 to 2025). "One exception was renal clear cell carcinoma, where a decrease in HMGA1 protein was accompanied by a decline in HMGA1 mRNA expression." (PMID 35805937, 2022). "Surprisingly, a few exceptions were also noted; for example, in kidney chromophobe and renal clear cell carcinoma, the HMGA1 was underexpressed." (PMID 35805937, 2022). "In addition, lncRNA ITGB2-AS1 promotes the progression of clear cell renal cell carcinoma by regulating miR-328-5p/HMGA1 axis." (PMID 35082972, 2022). "HMGA1 is a chromatin remodeling factor, and studies have found that HMGA1-mediated miR-671-5p targeting APC promotes the metastasis of clear cell renal cell carcinoma through the Wnt signaling pathway." (PMID 36941564, 2023).
ductal carcinomas (4 papers, 2012 to 2016). "These authors also reported that HMGA1 overexpression was comparable between ductal carcinomas of different histological grade, and was associated with c-erbB2 expression." (PMID 25859543, 2015). "A previous study has shown that HMGA1 is overexpressed in 60% of sporadic ductal carcinomas, but it is unclear whether HMGA1 is enriched in a particular molecular subtype." (PMID 23945276, 2013). "On the other hand, breast ductal carcinomas with high HMGA1 expression and with low apoptotic index (not shown) show HIPK2 cytoplasmic localization, meaning likely HIPK2 inactivation." (PMID 22889244, 2012). "Thus, immunostaining of breast ductal carcinomas with low HMGA1 expression and with high apoptotic index (not shown) results in HIPK2 nuclear localization." (PMID 22889244, 2012).
Hyperglycemia (4 papers, 2015 to 2023). An increased concentration of glucose in the blood. "HMGA1 expression level regulates insulin signaling in the liver, and restoring the expression level of G9a in leptin receptor gene-deficient mice not only elevates HMGA1 level, but also reduces hyperglycemia and hyperinsulinemia." (PMID 37008904, 2023). "In support of the role of HMGA1 in INSR gene transcription, in vitro investigations in beta-pancreatic cells demonstrated that sustained hyperglycemia impaired HMGA1 expression, a condition affecting INSR content in beta cells and, thus, insulin secretion." (PMID 30034366, 2018).
proliferative diabetic retinopathy (4 papers, 2016 to 2025). Advanced retinopathy due to diabetes mellitus characterized by the formation of new vessels in the retina. "The single nucleotide mutation rs139876191 in HMGA1 can down-regulate expression of VEGFA and inhibit proliferative diabetic retinopathy." (PMID 34527669, 2021).
squamous cell carcinoma (4 papers, 2013 to 2022). A carcinoma arising from squamous epithelial cells. "In squamous cell carcinoma, the HMGA1 expression level was lower in stage I than in stage II (p = 0.0330)." (PMID 35805937, 2022). "Our present analysis of the various large datasets provided by Oncomine showed that HMGA1 upregulation in a common phenomenon, concerning not only adenocarcinoma and squamous cell carcinoma but also large and small cell carcinomas of the lung." (PMID 35805937, 2022). "Lin and Peng detected higher levels of HMGA1 protein in the squamous cell carcinoma subtype compared to adenocarcinoma." (PMID 35805937, 2022). "In squamous cell carcinoma, only smokers and reformed smokers for <15 year groups differed significantly in HMGA1 expression level (p = 0.0217)." (PMID 35805937, 2022). "Frozen NSCLC tissue-based microarray analysis revealed that E2F6, TFDP1, SUV39H1, and HMGA1 are significantly upregulated in both the adenocarcinoma and squamous cell carcinoma samples." (PMID 24564251, 2013). "An increase in the median HMGA1 expression level was stated between stage I and stages II and III in adenocarcinoma, and between stages I and II in squamous cell carcinoma." (PMID 35805937, 2022). "We found that E2F6, HMGA1, IRF1, and TFDP1 were upregulated and RBL1, SUV39H1, and HNRPD were downregulated or aberrantly expressed in adenocarcinoma and squamous cell carcinoma, which are the sub-types of NSCLC." (PMID 24564251, 2013). "Therefore, combining the microarray and qPCR results, upregulation of E2F6, HMGA1, IRF1, and TFDP1 and downregulation or no expression of SUV39H1, RBL1, HNRPD can be used as diagnostic markers of NSCLC, and, in particular, adenocarcinoma and squamous cell carcinoma." (PMID 24564251, 2013).
thyroid tumor (4 papers, 2016 to 2020). A benign or malignant neoplasm affecting the thyroid gland. "HMGA1P6 is reported to be overexpressed in human pituitary and thyroid tumors, and regulates HMGA1 as a competing endogenous RNA15,17." (PMID 32127525, 2020). "The results revealed high expression of HMGA1 protein in these cells whose levels were comparable with those found in the thyroid tumor cells 8305C used as positive control; Human fibroblasts (HF) were used as low-expressing control." (PMID 29980789, 2018). "HMGA1 was stained in 98.6 % of thyroid tumors, predominantly in nuclear with faint cytoplasmic staining, and was stained in 60.0 % in normal thyroid tissue (P = 0.000)." (PMID 27008379, 2016).
acute lymphoblastic leukemia (3 papers, 2011 to 2025). Leukemia with an acute onset, characterized by the presence of lymphoblasts in the bone marrow and the peripheral blood. "Leukemic blasts from children with B-lineage, acute lymphocytic leukemia (ALL) also overexpress HMGA1 and similar downstream networks to those identified in preclinical models." (PMID 40076747, 2025). "In pediatric acute lymphoblastic leukemia (ALL), HMGA1 is overexpressed, with the highest levels at relapse." (PMID 40076747, 2025).
breast adenocarcinoma (3 papers, 2014 to 2022). "As expected, we found upregulation of H19, IGF2 and HMGA1 following HMGA1P7 overexpression in MCF7 cells (human breast adenocarcinoma cell line)." (PMID 27874091, 2016).
cholangiocarcinoma (3 papers, 2021 to 2024). A carcinoma that arises from the intrahepatic biliary tree (intrahepatic cholangiocarcinoma) or from the junction, or adjacent to the junction, of the right and left hepatic ducts (hilar cholangiocarcinoma). "In the present study, we observed that HMGA1 was commonly upregulated in cholangiocarcinoma and was associated with a poor prognosis." (PMID 34716319, 2021). "It has been shown that overexpression of HMGA1 confers radioresistance by transactivating RAD51 in cholangiocarcinoma." (PMID 39690136, 2024). "Our study identified HMGA1 as a novel transcription factor that induces RAD51 expression in cholangiocarcinoma." (PMID 34716319, 2021). "In this study, we provide the first evidence that HMGA1 is involved in homologous recombination repair through regulating RAD51 in cholangiocarcinoma." (PMID 34716319, 2021). "Thus, although the roles of HMGA1 in DNA repair are controversial, its expression and functional role in cholangiocarcinoma remain unclear." (PMID 34716319, 2021).
diabetic cardiomyopathy (3 papers, 2020 to 2022). Diabetic cardiomyopathy is a disorder of the heart muscle in people with diabetes. "This study aims to explore the functional role of HMGA1 in streptozotocin-induced diabetic cardiomyopathy and the underlying mechanism." (PMID 32123163, 2020). "It has been recently reported, in a mouse model of diabetic cardiomyopathy, that HMGA1 activates the transcription of miR-222, which targets p27 mRNA, as shown in other cellular models." (PMID 35504904, 2022). "In diabetic cardiomyopathy, HMGA1 inhibits autophagy by regulating the activity of the miR-222 promoter, thereby aggravating cardiac dysfunction." (PMID 34513822, 2021). "Taken together, our data indicate that HMGA1 aggravates diabetic cardiomyopathy by directly regulating miR-222 promoter activity, which inhibits P27/mTOR-induced autophagy." (PMID 32123163, 2020).
gallbladder carcinoma (3 papers, 2021 to 2022). "For example, lncRNA HIF1A-AS1 and ZEB1-AS1 were recently proved to be associated with HCC progression via ceRNA pattern, while lncRNA TTN-AS1 was demonstrated to act as a tumor promoter in gallbladder carcinoma by sponging miR-107 and upregulating HMGA1." (PMID 35241097, 2022). "Next, we measured HMGA1 expression in various biliary cell lines including normal biliary epithelium cell line HIBEpiC, the pCCA cell lines QBC-939 and FRH-0201, iCCA cell lines RBE and HCCC-9810, gallbladder carcinoma cell lines GBC-SD, NOZ and SGC-996." (PMID 33648560, 2021).
germ cell tumor (3 papers, 2010 to 2020). A benign or malignant, gonadal or extragonadal neoplasm that originates from germ cells. "Using qRT-PCR, we found that cultured cancer cells derived from a germ cell tumor (Tera-2 embryonal cancer cell or ECC line) have ∼50% lower HMGA1 mRNA levels compared to hESCs." (PMID 23166588, 2012).
Glucose intolerance (3 papers, 2009 to 2017). Glucose intolerance (GI) can be defined as dysglycemia that comprises both prediabetes and diabetes. "The mouse HMGA1 KO also exhibits reduced insulin receptor abundance but as part of a complex metabolic phenotype with mild glucose intolerance, hypoinsulinemia and enhanced insulin sensitivity." (PMID 28753127, 2017).
intestinal cancer (3 papers, 2015 to 2022). "Analysis of both mouse and human intestinal cancer specimens reveals that stem cell markers were significantly associated with loss of Let-7 miRNA expression, and that a number of Let-7 targets were elevated, including Hmga1 and Hmga2." (PMID 26244988, 2015). "To determine how Hmga1 disrupts tissue homeostasis in the intestines of transgenic mice and intestinal cancers overexpressing HMGA1, we examined its expression and function in our transgenic model and in intestinal organoids." (PMID 28452345, 2017). "It has also been shown that HMGA1 can directly interact with PD-L1, and upregulation of HMGA1 by PD-L1 can activate PI3K/Akt and MEK/ERK pathways to promote the development of colon and intestinal cancers." (PMID 36536279, 2022).